GRPR (gastrin releasing peptide receptor)
Diseases named in the same sentence as GRPR in open-access papers (continued):
Sharing a sentence is not in itself a finding about the gene and the disease.
prostate carcinoma (continued). "Additionally, our work revealed that GRPR plays an important role in anchorage-independent growth and invasion in the human prostate cancer cell lines tested, as GRPR silencing led to a significantly decrease in the invasive capacity of both LNCaP and VCaP cell lines." (PMID 26097883, 2015). "We have earlier reported the preclinical and clinical evaluation of the GRPR antagonist-based tracer [99mTc]Tc-maSSS-PEG2-RM26 aimed, first and foremost, at the staging of prostate cancer." (PMID 40871022, 2025). "The gastrin-releasing peptide receptor (GRPR)is strongly presented on the surface of various cancer cells, particularlybreast, colon, lung, pancreas, and prostate cancer." (PMID 39895089, 2025). "An in vivo trial further demonstrated that combining tracers targeting both GRPR and PSMA provides superior delineation of total tumour volume in prostate cancer patients." (PMID 40265741, 2025). "In addition, given that GRPR antagonists turned out to be more resistant to degrading proteases compared with their agonist counterparts, the shift toward antagonist-based radioligands led to the development of efficient agents, primarily for the visualization and treatment of prostate cancer." (PMID 40871022, 2025). "The gastrin releasing peptide receptor (GRPR) is a promising target for PET imaging due to its overexpression in multiple malignancies, including prostate cancer, breast cancer, gastrointestinal (GI) stromal tumors, and small-cell lung cancer." (PMID 40775579, 2025). "This study introduces new theranostic tools that combine the UniCAR peptide epitope E5B9 with the metabolically stable GRPR-targeting peptide bombesin antagonist BBN2 in monomeric and dimeric forms for imaging and treatment of prostate cancers." (PMID 40141329, 2025). "The resulting [68Ga]-labeled peptides demonstrated high and GRPR-specific binding to prostate cancer PC-3 cells, antagonistic behavior, and the IC50 values to GRPR were in the single-digit nanomolar range." (PMID 40775579, 2025). "From these datasets, we extracted gene expressions, including FOLH1, GRPR, FAP, and Harris Hypoxia, and estimated the proportions of different cell types—epithelial, endothelial, and prostate cancer (PC) cells—in the corresponding ST spots." (PMID 39629134, 2024). "Our findings revealed that GRPR expression was significantly higher in the stage of PIN and primary prostate cancer with GS = 6, but decreased in lymph node metastasis." (PMID 38880858, 2024). "In this study, we investigated the expression of three biomarkers (GRPR, PSMA, and NTR1) in different stages of precancerous lesions and prostate cancer patients (PIN, PCa, and lymph node metastasis)." (PMID 38880858, 2024). "We decided to investigate the potential advantages–shortcomings of the “radioligand cocktail” approach in human prostate cancer, prompted by the reported co-expression of NTS1R and GRPR in this frequently occurring cancer type." (PMID 39339259, 2024). "In this study, we successfully achieved the use of [212Pb]Pb-DOTAM-GRPR1, comprising the α-particle generator, 212Pb, combined with a GRPR-targeting peptide, GRPR1, in a prostate cancer model." (PMID 39327021, 2024). "GRPR is upregulated in many types of cancers, including prostate, breast, lung, and colorectal cancers, and can potentially detect PSMA-negative prostate cancers." (PMID 39456584, 2024). "Targeting the gastrin-releasing peptide receptor (GRPR)with thebombesin analogue RM26, a 9 aa peptide, has been a promising strategyfor cancer theranostics, with recent success in radionuclide imagingof prostate cancer." (PMID 39220525, 2024). "Our study aims to compare the expression of GRPR, PSMA, and NTR1 in patients with prostatic intraepithelial neoplasia (PIN), prostate cancer (PCa), and lymph node metastasis." (PMID 38880858, 2024).
prostate carcinoma (continued). "In the present work, we explored the advantages and disadvantages of using an equimolar [99mTc]Tc-DB7+[99mTc]Tc-DT11 cocktail for targeting prostate cancer using PC-3 cells and animal models, which are known to co-express the NTS1R and the GRPR." (PMID 39339259, 2024). "Utilizing ST data from prostate cancer tissue, we simulated PSMA, FAP, and GRPR-targeted RPTs with both beta- and alpha- emitting ligand accounting for the complex heterogeneities within the TME." (PMID 39629134, 2024). "It has been found that GRPR expression more clearly correlates to Gleason scoring than prostate specific membrane antigen (PSMA), with higher expression evident in early-stage prostate cancer and, most importantly, minimal expression in prostate hyperplasia." (PMID 38366299, 2024). "We implanted 2 × 106 GRPR+ (PC3, group 1 and group 2) and GRPR− (DU145, group 3 and group 4) prostate cancer cells subcutaneously to the right flanks of male nu/nu mice (N = 5 for each group)." (PMID 36733960, 2023). "Less bulky than monoclonal antibodies, bombesin analog peptides are also interesting vectors for prostate cancer radionuclide therapy as they target a different protein from PSMA, namely the gastrin-releasing peptide receptor (GRPR)." (PMID 37370743, 2023). "A lot of effort has been focused on targeting prostate cancer cell markers, such as the prostate-specific membrane antigen (PSMA) and gastrin-releasing peptide receptor (GRPR), to improve diagnosis and therapy." (PMID 37509170, 2023). "Among the explored prostate cancer cell markers are the prostate-specific membrane antigen (PSMA) and the gastrin-releasing peptide receptor (GRPR), which are also expressed in other malignancies, including breast cancer." (PMID 37175001, 2023). "The physiological expression of GRPr shows a different pattern compared to PSMA and is high in the pancreas, bladder, lymph node metastases, and bone lesions of prostate cancer." (PMID 38201600, 2023). "The development of radioligands targeting prostate-specific membrane antigen (PSMA) and gastrin-releasing peptide receptor (GRPR) has shown promising results for the imaging and therapy of prostate cancer." (PMID 36672390, 2023). "Their functionalization with a thiolated bombesin (BBN) peptide led to target-specific NPs (AuNP-BBN) with a high affinity for the gastrin-releasing peptide receptor (GRPR) and enhanced uptake in the human prostate cancer PC3 cell line overexpressing the GRPR." (PMID 35563666, 2022). "The gastrin-releasing peptide receptor (GRPR) is a promising molecular target for imaging and therapy of prostate cancer using bombesin peptides that bind to the receptor with high affinity." (PMID 35745647, 2022). "GRPR targeting potential of 68Ga- and 177Lu-labelled ProBOMB2—a novel BBN derivate—was investigated in preclinical models of GRPR-positive PC-3 human prostate cancer tumor-bearing male immunocompromised mice." (PMID 36077458, 2022). "Combination GRPR targeted radionuclide therapy and immunotherapy with 177Lu RM26 and trastuzumab, respectively, lead to the synergistic therapy of prostate cancer in mice models." (PMID 36077820, 2022). "This further strengthens the potential of GRPR as a target for PET and SPECT-imaging in prostate cancer, particularly at the oligometastatic stage." (PMID 33574368, 2021). "In summary, cobalt-labeled GRPR targeting agonist and antagonist peptides successfully imaged PC3 prostate cancers." (PMID 34359318, 2021). "GRPr and PSMA expression were compared on primary prostate cancer samples as well as patients providing evidence that the biodstribution for the two radioligands were distinct." (PMID 33258012, 2020). "Our AuNPs carry a bombesin analogue with affinity towards the gastrin releasing peptide receptor (GRPr), overexpressed in a variety of human cancer cells, namely PC3 prostate cancer cells." (PMID 31978954, 2020).
prostate carcinoma (continued). "In sum, our study provides a definitive proof of tumor-suppressive role of MME, links GRP/GRPR signaling to the control of prostate stem/progenitor cells, and shows how dysregulation of such signaling may promote formation of castration-resistant prostate carcinomas." (PMID 32205838, 2020). "Several radiotracers have been developed to target either GRPR or PSMA with the aim to detect and treat prostate cancer." (PMID 31340483, 2019). "Attractive targets for a more specific and sensitive imaging of primary prostate cancer are the prostate-specific membrane antigen (PSMA) and the gastrin-releasing peptide receptor (GRP-R)." (PMID 31161459, 2019). "The first proof-of-concept GRPR targeting study was conducted using a 99mTc-labeled BBN conjugate (RP527) for breast and prostate cancer imaging." (PMID 31398865, 2019). "Two such receptors are identified in prostate cancer cells: prostate-specific membrane antigen (PSMA) and the gastrin-releasing peptide receptor (GRPR)." (PMID 31398865, 2019). "Gastrin-releasing peptide receptor (GRPR) and prostate-specific membrane antigen (PSMA) are overexpressed in most prostate cancers." (PMID 31340483, 2019). "We recently have shown that GRPR is an ERG and ETV1 target gene in prostate cancer, using a genome-wide scale and exon-level expression microarray platform." (PMID 26097883, 2015). "Expression of GRPR, both at mRNA and protein levels, was detected in ERG and ETV1 rearrangement-positive prostate cancer cell lines VCaP and LNCaP, respectively." (PMID 26097883, 2015). "We recently have shown that gastrin-releasing peptide receptor (GRPR) is an ERG and ETV1 target gene in prostate cancer, using a genome-wide scale and exonlevel expression microarray platform." (PMID 26316886, 2015). "Similar to prostate cancers, lung cancers express GRP and GRPR where they promote tumor progression and metastatic spread through autocrine and paracrine mechanisms." (PMID 21745389, 2011). "While GRPR‐based imaging is particularly beneficial for detecting low‐grade prostate cancer and lesions unaffected by hormonal treatment, PSMA imaging is more effective in high‐grade prostate cancer and post‐hormone therapy cases." (PMID 40265741, 2025). "[177Lu]-Lu-LF1 shows promise as a therapeutic radioligand for GRPR-positive prostate cancer, offering high tumor uptake and rapid clearance from nontarget tissues." (PMID 41536273, 2025). "Overexpression of GRPR and GPRR signaling can stimulate growth of both androgen-dependent and -independent prostate cancer cells, in addition, it can indirectly promote angiogenesis and promote the mitosis of prostate cancer cells." (PMID 38880858, 2024). "Most interestingly, GRPR is highly expressed in early-stage prostate cancer with advantageously no expression in benign prostatic hyperplasia." (PMID 38675174, 2024). "Currently, GRPr imaging appears to be complementary to prostate-specific membrane antigen (PSMA) imaging in preclinical studies and preliminary human studies in patients with primary limited prostate cancer." (PMID 37285007, 2023). "Previous works have suggested that GRPr expression is higher in initial disease stages and that [68Ga]Ga-RM2 may be particularly valuable for detecting well-differentiated, slow-growing prostate cancer lesions." (PMID 38201600, 2023). "As a result, 40–200 nm monodisperse nanoparticles with neutral zeta potential showed high entrapment of DTX and GRP motif on the surface and enhanced specific binding of their hybrid carriers to prostate cancer cells, but not to GRPR-free cells." (PMID 36834867, 2023). "The results show targeting specificity enhanced by more than three-fold, compared to untargeted nanobubbles or prostate cancer cells not expressing GRPR." (PMID 36733960, 2023). "Several GRPR antagonists were developed for SPECT and PET imaging of prostate cancer." (PMID 37175001, 2023).
prostate carcinoma (continued). "Therefore, the investigation of prostate cancer cell markers beyond PSMA is still valid, including GRPR as an example." (PMID 37509170, 2023). "GRPR overexpression has been documented in 63–100% of primary prostate cancer samples and in the majority of lymph node and bone metastases, while most benign and hyperplastic prostate cells are GRPR negative." (PMID 37509170, 2023). "Since the GRPR-antagonist complex is not internalized after the binding, GRPR antagonists offer a unique opportunity to explore the pretargeting strategy using clickable bombesin antagonists for prostate cancer theranostics." (PMID 36559063, 2022). "Importantly, GRPR and PSMA expression are both affected by standard of care treatments applied in prostate cancer, including targeting the androgen receptor pathway and taxane-based chemotherapy." (PMID 34830920, 2021). "Accordingly, the application of anti-GRPR radioligands may represent a valid complementary approach to prostate-specific membrane antigen (PSMA) targeting for diagnosis and treatment of prostate cancer." (PMID 34830920, 2021). "Cell uptake studies in PC3 human prostate cancer cells were performed to confirm that the inclusion of the Gd3+ ions did not compromise the GRPr-mediated cellular uptake." (PMID 31978954, 2020). "Thus, GRPR- and VPAC1R-bispecific radiotracers should be able to increase the specificity and sensitivity of prostate carcinoma imaging as well as that of other malignancies expressing these receptor types such as breast cancer." (PMID 32751666, 2020). "The reason for developing agents comprising a bombesin-derived agent (targeting the GRPR) and a Glu-urea-Lys or Glu-urea-Glu structure motive (addressing the PSMA) for imaging of prostate carcinoma (PCa) results from the changes of the receptor statuses during progression of the disease." (PMID 32751666, 2020). "The presence of the BBN peptide provided specificity towards the gastrin releasing peptide receptor (GRPR) overexpressed in prostate cancer cells and did not compromise an extensive nuclear internalization." (PMID 32661612, 2020). "High GRPR expression was documented in the early, androgen-dependent stages of prostate cancer (PCa), but not in the hyperplastic prostate." (PMID 29097932, 2017). "Both GRPR and its specific ligand GRP (gastrin-releasing peptide), are known to be overexpressed in several human malignancies, including neuroblastoma, lung, breast, pancreatic, colorectal, gastric, esophageal and prostatic cancer." (PMID 26097883, 2015). "Currently, there is no knowledge about the expression of PSMA, EpCAM, VEGF and GRPR in locally recurrent prostate cancer after brachytherapy or external beam radiotherapy." (PMID 24727373, 2014). "High GRPR-density expression in prostate carcinomas and prostatic intraepithelial neoplasms and the absence of receptor expression in normal prostate tissue and benign hyperplastic prostate tissue has previously been reported." (PMID 24312607, 2013). "GRP and GRPR are expressed by NE cells in prostate cancer tissue and by prostate cancer-derived cell lines; BBS stimulates the growth of both orthotopic and ectopic prostate cancer cell xenografts in athymic nude mice through GRPR-mediated mechanisms." (PMID 21745389, 2011). "Inhibiting GRPR may provide an effective therapeutic alternative for decreasing COX-2 expression and activity in patients with recurrent prostate cancer." (PMID 21745389, 2011). "Finally, in prostate cancer (PCa), 99mTc-labeled iron oxide nanoparticles functionalized with prostate-specific membrane antigen (PSMA) and BBN showed high in vitro stability and enhanced affinity and specificity for PSMA- and GRPR-positive PCa cells." (PMID 40869454, 2025).
prostate carcinoma (continued). "Based on the GRPR overexpression in the early stages of the disease as opposed to healthy or hyperplastic surrounding tissue, GRPR-directed radiopharmaceuticals are expected to play a significant role in the management of prostate cancer, especially in primary and oligometastatic stage." (PMID 38366299, 2024). "Last, imaging (and therapy) of other GRPR-expressing tumour entities including breast cancer and gastrointestinal stromal tumours might further broaden the scope of applications for [99mTc]Tc-N4-BTG beyond prostate cancer." (PMID 38668903, 2024). "Their potential for imaging GRPR expression was evaluated through in vitro competition binding, positron emission tomography (PET) imaging, and ex vivo biodistribution studies in a preclinical prostate cancer model, and compared with a clinically validated GRPR agonist tracer, [68Ga]Ga-AMBA." (PMID 36838968, 2023). "Although the results of latter preclinical investigation agree with the known increased GRPr expression in low-grade prostate cancer, in vitro and preclinical results may not necessarily represent the imaging findings on humans." (PMID 35864350, 2023). "Our dual photoacoustic/ultrasound molecular imaging shows a more than three-fold enhancement in targeting specificity of the GRPR-targeted ICG nanobubbles, compared to untargeted nanobubbles or prostate cancer cells not expressing GRPR, in a prostate cancer xenograft mouse model in vivo." (PMID 36733960, 2023). "In the case of prostate cancer theranostics, one could initially assume that the advent of radiolabeled theranostic PSMA-inhibitors in the clinic has imposed a serious challenge on the application of GRPR-antagonist radioligands." (PMID 37242457, 2023). "Hence, GRPR-targeting may play an important complementary role to PSMA-targeting, for example, in the management of oligometastatic prostate cancer." (PMID 37509170, 2023). "Their potential for imaging GRPR expression was evaluated by in vitro competition binding, positron emission tomography (PET) imaging, and ex vivo biodistribution studies in a preclinical PC-3 prostate cancer model in mice, and compared with the gold standard, [68Ga]Ga-RM2." (PMID 35744904, 2022). "Likewise, GRPR expression is also not unique to the prostate nor to prostate cancer; the high absorbed pancreatic dose and diffuse low uptake throughout the gastrointestinal tract constitute a serious concern for therapy." (PMID 34830920, 2021). "GRPR-targeted radioligands may help to solve, at least in part, these clinical issues by complementing the PSMA PET/CT and radioligand therapy and improving the prostate cancer detection rate as well as therapeutic efficacy." (PMID 34830920, 2021). "As prostate cancer is to be considered a heterogeneous disease, it might be useful to take advantage of the information given by both target structures PSMA and GRPR." (PMID 32533273, 2020). "Thus, there may be utility for other prostate cancer targeted theranostics in addition to PSMA, especially in the GRPR class." (PMID 32582550, 2020). "While GRPR expression may not be as ubiquitous on prostate cancer cells as PSMA, there is no background target expression in the kidneys or salivary glands." (PMID 32582550, 2020). "To study peptide distribution and accumulation in solid tumors, we choose to study GRPr-targeting radiopeptides that bind with high affinity to GRPr-expressing tumor cells It has been shown in several prostate cancers and in PDX models of prostate cancer that the GRPr expression is high." (PMID 26769345, 2016). "Our study demonstrates the successful design of potent GRPR radioantagonists featuring non-linear, conformationally restricted structures, and holds strong potential to significantly expand the range of diagnostic and therapeutic radioligands available for PET imaging of prostate cancer." (PMID 40775579, 2025).
prostate carcinoma (continued). "Our study establishes a mechanistic link between GRPR activation and enhanced COX-2 expression in prostate cancer cell lines, and suggests that inhibiting GRPR may provide an alternative to non-steroidal anti-inflammatory drugs for inhibiting COX-2 in patients with recurrent prostate cancer." (PMID 21745389, 2011). "In the relatively near future, there may be additional PET radiotracers based on gastrin-releasing peptide receptor and fibroblast activation protein which may provide synergism to PSMA PET or have utility in those prostate cancers that express no or low PSMA expression." (PMID 39558122, 2025).